IL22 (interleukin 22)
Diseases named in the same sentence as IL22 in open-access papers (continued):
Sharing a sentence is not in itself a finding about the gene and the disease.
bacterial infection (continued). "IL-17A and IL-22 are known to contribute to the epithelial barrier function against bacterial infection through inducing the production of AMPs, including β-defensins and S100 proteins." (PMID 33920301, 2021). "Low level IL-22 production and signaling (during homeostasis) seems to strengthen epithelial barrier function, while increased levels of IL-22 induced during inflammation help clearing bacterial infections, such as shown for Citrobacter rodentium infection." (PMID 34603258, 2021). "The importance of the ILC3 subset in the context of viral infection has recently been reported by demonstrating that the presence of IL-22 can limit tissue damage and prevent secondary bacterial infections in the Influenza (Flu) disease." (PMID 34209845, 2021). "IL-22 also reduces lung inflammation and protects against secondary bacterial infection during IAV infection." (PMID 33906918, 2021). "IL-22 exerts functions, similar to IL-17; both cytokines contribute to the control of extracellular bacterial infections." (PMID 32695114, 2020). "In that model, neutralization of IL-22 led to failed control of bacterial infection compared with control mice." (PMID 32582219, 2020). "ILC3s counter bacterial infections through secretion of IL-22, which stimulates epithelial cells to produce antimicrobial peptides." (PMID 32685120, 2020). "For example, IL-22 was found to be induced in vivo by bacterial infections in rainbow trout, turbot, pompano and catfish, by vaccination, and by stimulation with PAMPs and recombinant cytokines (IL-1β and TNFα)." (PMID 31306696, 2019). "•IL-22+ cells were found in the gill epithelium of lamellae and interbranchial lymphoid tissue after bacterial infection." (PMID 31306696, 2019). "This lineage CD4+ T cell produces unique cytokines IL-17A and IL-22, which play roles in inflammation pathogenesis and against extracellular fungi and bacterial infection." (PMID 31001353, 2019). "•IL-22 transcript and protein expression is up-regulated in gills and PBLs in response to bacterial infection." (PMID 31306696, 2019). "In the current study, we evaluated the role of the cytokine IL-22 (known to play a protective role in bacterial infections) and type 3 innate lymphoid cells (ILC3s) in regulating inflammation and mortality in Mtb-infected T2DM mice." (PMID 31809521, 2019). "IL-22, a member of the IL-10 cytokine family, has been demonstrated to play an important role in mucosal immunity in protecting bacterial infections and regulating microbiota in the gut." (PMID 29329335, 2018). "The IL-23 / IL-22 / IL-18 axis is essentially involved in host defence and in mediating and regulating inflammatory immune responses upon parasitic and bacterial infection." (PMID 27322540, 2016). "IL-23 stimulates the production of IL-22 during bacterial infections, and IL-22 expression by pulmonary NK cells is induced by IL-23 in vitro." (PMID 27303405, 2016). "Interleukin-22 plays an important protective role in host defense responses during bacterial infections." (PMID 27303405, 2016). "Given the established role of IL-22 in bacterial infections, the interaction between viruses and bacteria should also be considered when manipulating IL-22 in virus-infected individuals." (PMID 27303405, 2016). "As IL‐22‐producing group 3 ILCs protect from intestinal bacterial infection, we challenged RAG2−/− mice on eRapa or Eudragit for 1 month with the flagellated bacterium C. rodentium as described." (PMID 26315673, 2015). "So far, IL-22 was known to plays a fundamental role in the elimination of bacterial infections at border surfaces of the body and to protect tissues from damage." (PMID 26674616, 2015). "Upon screening for the expression of cytokines known to regulate intestinal defense mechanisms, IL-6 and IL-22 revealed strong induction after bacterial infection." (PMID 25799189, 2015).
bacterial infection (continued). "IL-22 enhances the innate immunity of epithelia and plays a fundamental role in the elimination of bacterial infections at body surfaces." (PMID 26674616, 2015). "Some human and mouse studies have actually shown IL-17- and IL-22- secreting ILC3 can become IFN-γ-secreting cells with T-bet acquisition induced by bacterial infection." (PMID 25503264, 2014). "It is increasingly recognized that IL-17, in combination with IL-22, is crucial for protection against bacterial infections in mucosal tissues, and for maintenance of the mucosal barrier by promoting intestinal epithelial tight junction integrity." (PMID 25364618, 2014). "Th17 cell lineage produces not only IL-17A but also IL-22, both of which contribute to the controlling of extracellular bacterial infection by the induction of a powerful immune response." (PMID 24899787, 2014). "Th22 cells are mostly localized to mucosal tissues, and are crucial for protecting host mucosal tissues against bacterial infections by their IL-22 production." (PMID 25364618, 2014). "Here we show that the cytokine IL-22, which was previously known to be involved in the defence against bacterial infections in the gut, is also involved in the defence against intestinal worms." (PMID 24130494, 2013). "IL-22 is central to host protection against bacterial infections at barrier sites, and IL-22 production was strictly IL-23 dependent." (PMID 24376306, 2013). "In this study we show that IL-22, a cytokine important in defence against bacterial infections in the intestinal tract, is also a critical mediator of anti-helminth immunity." (PMID 24130494, 2013). "IL-22 signaling has been shown to control bacterial infection by helping to mount antimicrobial immune responses." (PMID 22952908, 2012). "Surprisingly, in contrast to its protective role in bacterial infection, IL-22 was detrimental to mice when challenged with WNV." (PMID 22952908, 2012). "Exposure to IL-22 leads to an expression of host defense genes in humans and mice and neutralization of IL-22 resulted in exacerbation of bacterial infections, suggesting a protective role in mucosal/epithelial host defense." (PMID 21789181, 2011). "Like IL-22, LTα is also involved in the induction and maintenance of Fut2 expression, and Fut2 can subsequently catalyze epithelial fucosylation in the gastrointestinal tract, which has a role in preventing bacterial infection." (PMID 41467015, 2025). "IL-22 protects against parasitic and bacterial infections by inducing epithelial IL-1834,35." (PMID 38383607, 2024). "Apart from its protective role against intestinal bacterial infections, IL-22 may also have detrimental effects on IBD." (PMID 39309440, 2024). "Furthermore, most studies on IL-22-related therapy of bacterial infections highlighted the effects of TLR ligands or agonists, which offered broad prospects for the clinical application of TLR ligands." (PMID 36839448, 2023). "IL-22 is important for host protective immunity to both viral and bacterial infections." (PMID 37896822, 2023). "In addition, VD induced the expression of AMP in zebrafish intestine by activating IL-22 signal transduction dependent on microbial population, thus fighting bacterial infection." (PMID 38008755, 2023). "Therefore, Th22/IL-22 exerts a crucial effect on regulating the immune response to viral and bacterial infections." (PMID 36839448, 2023). "Moreover, it has been demonstrated that GCs are able to suppress IL-22 production in a mouse model of bacterial infection, while they are unable to suppress IL-22 production in a Th17-adoptive transfer model of airway inflammation." (PMID 35251043, 2022). "Additionally, during bacterial infection ILC3-derived IL-22 is required for bacterial clearance by regulating antimicrobial gene expression in epithelial cells." (PMID 36430676, 2022).
bacterial infection (continued). "As such, it stands to reason that the regenerative properties of IL-22 secreted by ILC3s may function in prevention of secondary bacterial infections." (PMID 33968082, 2021). "Specifically, the downregulated genes are related to neutrophil cell migration (mpx, sgk1), leukocyte recruitment (Irg1l), macrophage chemotaxis to the site of bacterial infection (Cxcr3.2), mucus production (cftr), wound healing, and protection against microbes (il22)." (PMID 34066767, 2021). "Mechanisms by which IL-22 mediates pathogen clearance, in the case of bacterial infection, are mostly unknown." (PMID 32582219, 2020). "The IL-22-mediated responses to bacterial infection have well been documented in fish." (PMID 33178219, 2020). "Elevated levels of IL-22 may be due to its protective function against bacterial infections and tissue antigens or, its increased level may contribute to the pathogenesis of the OLP." (PMID 33344684, 2020). "However, contrary to IL-22 protective role against bacterial infections, one study done on BALB/c mice, implied its dispensable role in immunity against opportunistic pathogens like Mycobacterium avium and Mycobacterium tuberculosis." (PMID 33042126, 2020). "On the other hand, IL-22 and IL-26 expressions were shown to be higher in transgenic epinecidin-1 zebrafish 12 h after bacterial infection, suggesting that both IL-22 and IL-26 may be the key immune mediators released by transgenic zebrafish muscle." (PMID 31824449, 2019). "TNF-α and IL-6 are typical pro-inflammatory cytokines and have been used as potential markers for ongoing bacterial infections in piglets, while IL-22 is essential for maintaining mucosal barrier homeostasis against specific pathogens by eliciting innate defense response." (PMID 31286936, 2019). "However, it is clear that at least another population of cells is present in the lamellae that also rapidly upregulate IL-22 expression in response to bacterial infection." (PMID 31306696, 2019). "Thus, the RA–HIC1 axis is critical for immunity to intestinal bacterial infection by regulating IL-22-producing ILC3s in the intestine." (PMID 29470558, 2018). "Generally, IL-22 promotes epithelial innate immune mechanisms, which can either be harmful or protective: IL-22 contributes to host defense against extracellular bacterial infections, tissue homeostasis and inflammation, in particular at epithelial barriers like bowel, lung and skin." (PMID 26107738, 2015). "In addition, Th22 cells are important contributors to mucosal host defense, and IL-22 is central to host protection against bacterial infections at barrier sites." (PMID 24376306, 2013). "The roles of IL-22 in inflammation and bacterial infections are diverse." (PMID 22952908, 2012). "Importantly, CD4+ T cells could secrete IL-22, which can aid in intestinal resistance to bacterial infection." (PMID 37067423, 2023). "Thus, these ILC-like cells in zebrafish may possibly resemble human and mice NCR + ILC3s in key ways, including IL-22 expression in response to bacterial infection." (PMID 34603258, 2021). "The focus here was on mucosal defences and whether IL-22 protein expression can be up-regulated in response to bacterial infection, and the analysis gives some intriguing results in terms of the variety of cell types that seem capable of producing IL-22 in fish." (PMID 31306696, 2019). "Similarly, in the present study, high expression of IL-22, particularly in the intestine during post challenge with A. salmonicida may also point to an immunological role of IL-22 in the intestine during bacterial infection." (PMID 26217339, 2015). "Interestingly, IL-22 enhances the expression of antimicrobial proteins in bacteria infection, suggesting that IL-22 may play a role in host defense against bacterial infection in skin and gut." (PMID 24824519, 2014).
bacterial infection (continued). "Since IL-22 is important in controlling bacterial infections in the gut, such as Citrobacter rodentium, the enrichment of TH22 as well as TH17 cells in the cecum may indicate the presence of potentially pathogenic bacteria in this region that are actively restrained by the mucosal immune response." (PMID 22829946, 2012). "It is generally known that IL-22, particularly IL-22 secreted by CD4 T cells, plays a more important role on the defense against bacterial infection and the protection of intestinal crypt epithelial cells." (PMID 37067423, 2023). "IL-22 production in sublethal H3N2 influenza virus infection is known to limit lung inflammation and specifically subsequent secondary bacterial infections." (PMID 33042126, 2020). "Other data revealed the involvement of IL-22Fc therapy in liver regeneration by reprogramming the regenerative pathways and attenuation of bacterial infection that ameliorated ACLF, which suggests the therapeutic potential for IL-22 in these patients." (PMID 33117329, 2020). "IL-22 is well-known for its hepatoprotective, pro-regenerative, and antimicrobial abilities, while ACLF is associated with hepatocyte damage, impaired liver regeneration, and bacterial infection; therefore, IL-22 treatment could benefit the problems that arise in ACLF." (PMID 33117329, 2020). "Although, a defect in the colonic patches in Nfkb2−/− mice could impair IL-22 mediated protective responses, our cell-intrinsic crosstalk model explained that the reported epithelial requirement of LTβR is in sustaining RelA NF-κB response during bacterial infection." (PMID 25905673, 2015). "In addition to its regulatory role in the expression of S100A9 and lipocalin-2 as we reported here, whether IL22 also contributes to urothelium defense mechanisms against bacterial infection by regulating HUC production of HA or HUC expression of TLR4/CD14 remains to be elucidated." (PMID 25354343, 2014). "In conjunction with previous studies, IL-22 has been shown to inhibit the activation of the NLRP3 inflammasome by suppressing the synthesis of NLRP3 and Caspase-1 proteins, thereby attenuating mammalian bacterial diseases and tissue injury." (PMID 39211040, 2024). "Moreover, IL-22 was involved in VD-induced AMP-expression and host defense to bacterial infection in zebrafish, since VD-induced immune responses were diminished in IL-22 KO fish." (PMID 36879441, 2023). "It has been shown using zebrafish that knock-down of IL-22 by morpholino in larval zebrafish in the absence of bacterial infection, tended to increase mortality." (PMID 34603258, 2021). "Correspondingly, lack of IL-22, or IL-22 receptor, contributes to a heightened inflammatory milieu in the intestinal epithelium, as well as increased sensitivity to bacterial infection due to increased systemic dissemination of bacteria." (PMID 31770366, 2019). "IL-22 is a more recently discovered cytokine that plays a protective role in bacterial infections by signaling to non-immune cells only, such as epithelial cells of the gastrointestinal tract and skin." (PMID 22911651, 2012). "Interestingly, IL-22 up-regulation after Listeria monocytogenes infection was seen in murine model, though, no clear effects on both primary and secondary bacterial infection were observed." (PMID 33042126, 2020). "We next studied the numbers of IL-22 positive cells by flow cytometry, and found that their numbers increase following stimulation of peripheral blood leucocytes (PBL) in vitro with killed bacteria, PHA and IL-21, and in vivo in blood and gills after bacterial infection." (PMID 31306696, 2019). "However, the cellular sources of IL22 in the bladder have not been delineated, and the role of IL22 in bladder defense in the context of bacterial infection is unknown." (PMID 35845169, 2022).
inflammation (48 papers, 2011 to 2026). Aberrant reaction of the microcirculation characterized by movement of fluid and leukocytes from the blood into extravascular tissues. "This indicates pathological effects of IL-17A as well as of IL-22 that have been also implicated in other situations such as progressive airway inflammation in a murine model of bleomycin-induced airway inflammation." (PMID 28222146, 2017). "A recent study in pulmonary lavage samples from patients with bronchial asthma revealed that IL-22 concentrations are elevated, further supporting that IL-22 is a disease-associated cytokine detectable in lavage and associated with lung inflammation, as seen in our study." (PMID 27388918, 2016). "At the same time it was noticed that in all cases the level of IL-22, which is intimately associated with lung inflammation, was always higher within each IgE positive sub-group than that in the corresponding IgE negative one, although the differences were not always statistically significant." (PMID 23330224, 2012). "Nevertheless, some studies still demonstrated a protective role for endogenous IL-22 against liver inflammation and fibrosis, particularly in MCD-induced MASH, but such effect was contingent on the absence of the IL-17 cytokine (Il17a-/-)." (PMID 39156888, 2024). "To confirm the role of IL-22 as a pro-inflammatory cytokine in the airway lung inflammation, we evaluated if the levels of this cytokine would be reduced after a mixed allergen-specific and allergen-free immunotherapy." (PMID 37445595, 2023). "Previous studies supported our findings that epicutaneous ovalbumin sensitization-stimulated airway inflammation is reduced by Il22 gene deletion or IL-22-neutralizing antibody pretreatment." (PMID 35216377, 2022). "In chronic ozone exposure-induced airway inflammation and hyperreactivity, recruitment of IL-22-producing cells including ILC3s, NK cells, and T cells was modulated by AhR, resulting in the inflammation control." (PMID 33718260, 2021). "Cytokines are involved in asthmatic chronic airway inflammation, especially those derived from the lymphocyte, which acts on epithelial cells, such as cytokine interleukin (IL)-22." (PMID 34836520, 2021). "The IL-23 pathway is involved in intestinal inflammation in several mouse models and IL-22 has a protective effect in some models of intestinal inflammation." (PMID 27645534, 2016). "The protective effect of ILC3-derived IL-22 in gut inflammation was demonstrated in several mouse models." (PMID 27645534, 2016). "For example, while IL-22 can act synergistically with IL-17a in promoting pathological airway inflammation, both contribute to protective antimicrobial peptide expression in the skin." (PMID 26107738, 2015). "In order to evaluate the effector function of endogenous IL-22 after onset of joint inflammation, anti-IL-22 antibody was administered in arthritic mice." (PMID 24676270, 2014). "By contrast, IL-22 is a protective agent for airway inflammation, and recombinant IL-22 can inhibit eosinophilic airway inflammation and the production of Th2 cytokines." (PMID 25289045, 2014). "Murine models of airway inflammation have shown that IL-22 can be pro-inflammatory (and thus pathological) in the presence of IL-17A but in the absence of IL-17A can be anti-inflammatory/tissue protective." (PMID 23555269, 2013). "IL-22 has been shown to act synergistically with IL-17A to promote acute pathological airway inflammation." (PMID 23476100, 2013). "On the other hand, Flavell and colleagues suggested that IL-22 can protect hepatocytes during acute liver inflammation." (PMID 21789181, 2011). "In vitro, IL-22 has a pro-inflammatory, hyperplastic effect on keratinocytes, and it was reported that IL-22 mediates IL-23-induced dermal inflammation and acanthosis in mice, similar to the changes seen in psoriatic skin lesions in humans." (PMID 21789181, 2011).